EGFR (epidermal growth factor receptor)
Diseases named in the same sentence as EGFR in open-access papers (continued):
Sharing a sentence is not in itself a finding about the gene and the disease.
tumor (continued). "All four tumours were negative for KRT5/6 protein but positive for EGFR staining." (PMID 25633981, 2015). "Furthermore, a decrease in tumor cell proliferation and angiogenesis and increased apoptosis have been described in in vitro and in vivo uLMS models after treatment with vandetanib, a VEGFR2/epidermal growth factor receptor (EGFR) inhibitor." (PMID 26576131, 2015). "Although the anti-angiogenic and anti-EGFR effects of EFEMP1 may account for its anti-tumor effect in most cancer types, EFEMP1's tumor-promoting role has been related to activation of NOTCH signaling, and hence is likely associated with conditions in the stem-like cancer-cell context." (PMID 26307682, 2015). "It is plausible that mCRC patients whose tumours are negative for EGFR IHC indeed have elevated pEGFR which may explain why a subgroup of these total EGFR negative patients respond to anti-EGFR therapies." (PMID 26149458, 2015). "Furthermore, histopathological characterization of P2-HTX revealed that the HTX successfully conserved key morphological and molecular characteristics of original parental (P0) tumours, including the expression of proliferation marker (Ki-67), glucose transport (GLUT1), phospho-EGFR and phospho-AKT." (PMID 25721094, 2015). "Thus, one would assume that while HER-3 positive tumor is killed by HER-3 reactive T cells, HER-3 negative tumor that activates other signaling pathways such as c-Met, EGFR, or HER-2 can still survive and become a major population." (PMID 26538233, 2015). "In vitro studies have shown that tumor cells harboring the most prevalent HER2YVMA are able to activate EGFR in a ligand-independent fashion and irrespective of the presence of an activating EGFR mutation." (PMID 26102513, 2015). "Age, sex, tumor size, β-catenin and EGFR had no prognostic significance." (PMID 26215716, 2015). "An intriguing aspect of our case is the “evolution” of the tumor first to a pure squamous histology in the brain metastatic site in the absence of any selective pressure by an EGFR tyrosine kinase inhibitor followed by a later local recurrence with pure adenocarcinoma histology." (PMID 26366316, 2015). "Twenty-four of the NGS-screened 29 patients were monitored, and the tumor responses and PFS clustered correspondingly; 5 of 10 (50%) patients with short PFS had progressive disease whilst on EGFR-TKI treatment and 13 of 14 (92.9%) patients with long PFS had a partial response to EGFR-TKIs." (PMID 25823662, 2015). "Furthermore, although one tumor contained mutations in both KRAS and EGFR, the KRAS mutation, D33E, is not known to be activating." (PMID 26047463, 2015). "While significant tumor regression was observed in the first week, tumors started to re-grow after 5 weeks of continuous treatment, with progressively increasing growth rate, consistent with the manifestation of a rescue pathway independent of EGFR." (PMID 26381735, 2015). "However, upon disease progression on EGFR TKI therapy, a striking increase in MET activation was observed in tumor cells from patient 006-010, possibly reflecting a compensatory mechanism for tumor growth." (PMID 26439803, 2015). "Cetuximab, an IgG1 monoclonal antibodies, can bind with EGFR protein of tumor cell by its Fab fragment, and its Fc fragment engages FCGR on an immune cell to activate the process of ADCC, eventually resulting in attacking and eliminating the cetuximab-coated tumor cell." (PMID 26363448, 2015). "In addition, we confirmed here that p-EGFR staining intensity between the stroma and tumor cells is strongly correlated in IBC patients but not correlated in non-IBC patients." (PMID 25887413, 2015). "Among patients with liver involvement, those with EGFR mutated tumors experienced a significantly superior OS compared to subjects with EGFR wild-type neoplasms [median OS not reached (95% CI not reached (N.R.)] vs. 13 months (95% CI 10.2–15.7), respectively; (HR = 0.06; p = 0.001)." (PMID 26248464, 2015).
tumor (continued). "In addition, blocking of EGFR/HER1 has no impact on the HER2, HER4, and JAK/STAT pathways (by-pass signaling pathways), in which activation of STAT3 is associated with tumor growth and malignancy." (PMID 25674538, 2015). "One possible explanation for the failure of these studies is that tumor cells that were driven to G0/G1 phase by EGFR TKIs may not be sensitive to cytotoxic chemotherapy." (PMID 26493267, 2015). "The loss of PTEN and increase in expression of other ERBB receptors may render EGFR signaling dispensable in the tumor, allowing growth and survival without EGFR signaling and thus negating the therapeutic viability of EGFR-targeting therapies in these cases." (PMID 25688333, 2015). "89Zr-cetuximab uptake did not correlate with EGFR expression levels, implying that pharmacokinetic and pharmacodynamic factors might influence cetuximab accumulation in the tumor." (PMID 26309164, 2015). "Our results show that OVCAR-5 cell line does not display invasive capacity in collagen gels, suggesting EGFR/Her-2 oncogenic expression may be a primary factor in the aggressiveness of tumour invasion in 3D gels." (PMID 26141064, 2015). "Interestingly, in the US in 2010, of those patients with mutant KRAS tumor status, only 86% were not treated with EGFR-targeted therapies, suggesting that 14% received anti-EGFR-treatment." (PMID 26491871, 2015). "Dephosphorylation of EGFR at EGFR-Y1068 and -Y1086 sites inactivated the PI3K/Akt signaling cascade and subsequent down-regulation of downstream pro-angiogenic and -invasive proteins (VEGF, IL6, and IL8) and suppressed tumor cell proliferation, angiogenesis, and invasion." (PMID 25970784, 2015). "To identify a better therapeutic target for this highly malignant tumor, we first reported the novel mechanism that long non-coding RNA HOTAIR regulates cell cycle progression and invasion through an NLK/β-catenin axis in GBM samples with different EGFR statuses." (PMID 25823657, 2015). "Tumor #2 gave rise to EGFR amplification in the AD component, but not the SQ component." (PMID 26068980, 2015). "Studies in vitro and in vivo using xenografted mice with cell lines over-expressing EGFR and HER2 have shown that lapatinib inhibits tyrosine phosphorylation in catalytic domain of EGFR and HER2 and prevents ERK1/2 and AKT activation which induces apoptosis of tumor cells." (PMID 26635612, 2015). "Notably, increased methylation level at EGFR promoter was found in tumour tissues than the corresponding adjacent noncancerous." (PMID 25959250, 2015). "In addition, upregulation of tenascin-C and p-EGFR was observed in the recurrent tumors and inhibiting p-EGFR signaling significantly delayed recurrence without affecting initial tumor regression." (PMID 26581390, 2015). "Furthermore, our studies indicate an important and novel role for FABP5 in the host and the tumor cell and that targeting FABP5 may prove a viable target to attack EGFR-enhanced TNBC metastasis." (PMID 25779666, 2015). "This multivalent ligand strategy has been validated for targeting numerous types of tumor cells overexpressing surface biomarkers such as folic acid receptor (FAR), riboflavin receptor, αvβ3 integrin, prostate-specific membrane antigen (PSMA), and epidermal growth factor receptor (EGFR)." (PMID 25590303, 2015). "Note, two of the significantly regulated tumour proteins, i.e. CRK and PEBP1 are members of the EGFR1 signalling pathway with PEBP1 also functioning as a master regulator while the other regulated proteins are connected to EGFR signalling through cross-talk among the pathways." (PMID 25872475, 2015).
tumor (continued). "The role of EGFR in HCC seems to be more complex than initially believed, particularly because EGFR expression is not restricted to tumor cells, but EGFR was also demonstrated to be expressed on sinusoidal endothelial cells, as well as on Kupffer cells and liver macrophages." (PMID 26729094, 2015). "However, the same dose of P7170 was not very effective in mice bearing erlotinib-insensitive H1975 [EGFR T790M, L858R; KRAS wild type; PIK3CA wild type] xenografts, but treatment with a15 mg/kg dose resulted in a significant tumor growth inhibition (92% TGI, p < 0.001)." (PMID 25466244, 2014). "The observed anti-tumor activities of celastrol and its derivatives both in vitro and in vivo promoted degradation and decreased phosphorylation of protein kinases that are known to be highly activated in HCC cells, such as Raf family proteins, AKT, MEK1/2, CDK4, and EGFR." (PMID 25051375, 2014). "The limited number of tumor cases may be the reason for the EGFR amplification was not involved in the Cox regression of small cell GBM and PNET." (PMID 24986561, 2014). "Furthermore, we found that combined inhibition of PI4KIIα and EGFR suppressed both PI3K/AKT and MAPK/ERK pathways, and resulted in downregulation of multiple oncogenes like PRDX2, FASN, MTA2, ultimately leading to suppression of tumor growth." (PMID 24801752, 2014). "A reason for the variation in published EGFR GCN results may be tumor heterogeneity, which has not been addressed in earlier studies." (PMID 24940619, 2014). "Like HER2 amplification and KRAS mutations, rare MET-amplified cells were found in pretreatment tumor material from one out of three patients with MET-driven acquired resistance, suggesting that preexisting clones were selected under the pressure of anti-EGFR therapy." (PMID 24811491, 2014). "Moreover, activation of different two receptors, EGFR and amplified KIT (both of which could induce crizotinib resistance), also co-existed in one crizotinib-resistant tumor." (PMID 24952482, 2014). "However, neither EGFR expression by IHC nor EGFR gene copy number by FISH in the primary tumor were found to be predictive of response in two retrospective analyses." (PMID 25105871, 2014). "Our clinical data suggest that PHD3 loss by genetic/epigenetic alterations could play a complementary role as an alternative EGFR-activating mechanism and may be particularly relevant for tumours without EGFR amplification." (PMID 25420773, 2014). "Patients were required to have an EGFR negative primary tumor and EGFR positivity on CTCs." (PMID 24670368, 2014). "Therefore, the characteristics of this patient (Caucasian ethnicity, male gender, cigarette smoking history and no severe skin rash) did not represent the well-known predictors of best response to EGFR-TKIs." (PMID 24661457, 2014). "We demonstrate that EGFR expression is regulated by RBM5 in vivo and in vitro in a direct or indirect way, and that may be one of the predominant mechanisms by which RBM5 mediated tumor suppression." (PMID 25441176, 2014). "We also found that when EGFR is activated, some tumor cells do not show C/EBPβ activation." (PMID 25229239, 2014). "Furthermore, the effect of erlotinib may also potentially be due to inhibition of proangiogenic factors (VEGF, IL-8) by EGFR inhibitors, given that activation of the EGF receptor on tumor cells is known to induce the production of VEGF." (PMID 24624093, 2014). "No clear correlation has been found between EGFR expression and tumour location or histotype." (PMID 24454858, 2014). "No EGFR copy number increase was found in EGFR wild type tumor samples." (PMID 24885034, 2014). "Thus it is possible that C/EBPβ is not activated in some tumor cells despite there having been EGFR activation." (PMID 25229239, 2014).
tumor (continued). "Several molecular mechanisms are involved in the resistance to anoikis of tumor cells, including survival signaling driven by PI3K and NF-κB pathways, the expression of anti-apoptotic proteins such as Bcl-2, and the hyperactivation of tyrosine kinase receptors such as EGFR and ErbB2." (PMID 25788857, 2014). "Thus, ligand-induced activation of EGFR or HER3 and formation of heterodimers with HER2 may play an important role in tumor growth and resistance to therapy." (PMID 25216528, 2014). "Interestingly, there were some tumor cells that exhibited EGFR activation but no C/EBPβ activation (arrow heads)." (PMID 25229239, 2014). "The positive IHC expression of EGFR cases accounted for 91.18%, 86.67% and 71.43% of MBs, small cell GBMs and PNETs respectively, and there was no statistical different between 3 tumor subtypes (P = 0.0636)." (PMID 24986561, 2014). "CD44 may also inhibit tumor progression by binding to high molecular weight hyaluronan and promote its interaction with hypophosphorylated Merlin, inhibit RAS activation, inhibit CD44–ERM interactions and suppress EGFR activation." (PMID 24760019, 2014). "Moreover, administration of an anti-EGFR drug during the active phase of the day, rather than the resting time, less effectively inhibited tumour growth in animals." (PMID 25278152, 2014). "In addition, our data showed that there was no synergistic effect between KPT-185 and EGFR-TKI (gefitinib) treatment on tumor cell viability inhibition." (PMID 24595136, 2014). "Tumor weight measured at the completion of the efficacy study (day 33) corroborated the trend indicated by tumor volume measurement where EGFR-targeted nanoparticle treated tumor shows minimum mass (p < 0.001) compared to non-targeted and non-PEG gelatin nanoparticle treated tumors." (PMID 24507760, 2014). "By contrast, ER expression was not identified to correlate with EGFR expression or tumor size; therefore, ER and PR may differ with regard to their influence on lung carcinogenesis." (PMID 25364399, 2014). "Along with previous experiments on combined fractionated irradiation and EGFR-TK inhibition, it appears likely that TKI do not affect survival of tumour cells that can cause recurrences but can lead to a good palliative effect by proloning tumour growth for a reasonable amount of time." (PMID 25444177, 2014). "Furthermore, EGFR gene amplification as a result of polysomy of chromosome 7 was found to be negatively correlated with poor tumor differentiation (52.9 vs. 23.5%; P=0.023; data not shown)." (PMID 25013472, 2014). "IgA2 EGFR significantly decreased tumour growth until Day 14 in FcαRI Tg but not in WT SCID mice." (PMID 23918228, 2013). "The anti-tumour activity of IgA EGFR antibodies has not been tested in vivo before." (PMID 23918228, 2013). "Thus, a fully human antibody (and not a human-mouse chimera) against EGFR, panitumumab has been developed and has also been shown to inhibit tumor growth in vivo." (PMID 24276379, 2013). "It will be therefore interesting to investigate how GAPDH could contribute with FDG uptake level and tumor stage in building a composite prognostic marker, possibly also correlating it with the status of known NSCLC oncogenic genes (PI3K, EGFR, KRAS, ALK, etc.)." (PMID 23988223, 2013). "Due to the inconsistent expression pattern of circulating EGFR ECD in different tumor types, EGFR alone may not be a suitable maker for cancer diagnosis or prognosis." (PMID 23990977, 2013). "This notion is support by breast cancer patients who experienced tumor progression after treatment with trastuzumab (Herceptin, Genentech), a monoclonal antibody targeted against HER2, have demonstrated responses to the dual EGFR and HER2 tyrosine kinase inhibitor lapatinib (Tykerb, GSK)." (PMID 23405260, 2013).
tumor (continued). "Our data suggest that EGFR-dependent signaling would be an important therapeutic target for NSCLC treatment, based on the results such as the requirement of MEK/ERK signaling in the invasive properties of EMT-induced A549 cells and the local activation of ERK at the invasive tumor fronts." (PMID 24318272, 2013). "We genotyped the EGFR polyA repeat in non malignant colorectal tissue or blood from 429 patients with CRC corresponding to different groups of CRC patients selected or not on age of tumor onset and/or familial history and/or MSI." (PMID 23565769, 2013). "Thus, it would be an important advantage if culture conditions for EGFR non-amplified and EGFR amplified primary GBMs would be identical in order to preserve their characteristics and the original tumor genotype." (PMID 24294177, 2013). "Experiments using a murine EGFR (mEGFR)-antagonistic antibody in a syngeneic preclinical model demonstrated that the anti-metastatic effect produced by treatment with this mab is mediated by T cells, since depletion of CD4+ and CD8+ T cells abrogated the anti-tumor effect." (PMID 23637683, 2013). "However, in 22B cells, EGFR phosphorylation was not decreased in a significant dose-dependent manner when treated with gefitinib, which suggests that the 22B tumor cells are tolerant to gefitinib." (PMID 23748900, 2013). "Persistent EGFR signaling, coupled with the autocrine induction of membrane-bound HRG, contributed to a switch in the regulation of cell survival from HER2-HER3-PI3K in treatment-naïve HER2+ breast cancer cells to an HRG-driven EGFR-HER3-PI3K-PDK1 signaling axis in lapatinib-resistant tumor cells." (PMID 24044505, 2013). "However, mechanism of EGFR overexpression in this tumor having absence of genetic alterations in EGFR has not yet been elucidated." (PMID 23675485, 2013). "Therefore, combined treatment with EGFR and AXL inhibitors might effectively abrogate the growth of tumor cells." (PMID 24369725, 2013). "EGFR protein was not significantly different between tumor and mucosa tissue." (PMID 24171795, 2013). "In addition, the lack of EGFR-mediated growth-stimulatory activity makes EGFt an excellent delivery agent to target toxins to tumours over-expressing EGFR." (PMID 23935985, 2013). "Given the similarities in clinical progression and therapy as well as tumor biology including EGFR signaling, molecular aspects of cancer progression and angiogenesis, and clinical manifestations of malignant osteolysis, FOSCC is a biologically relevant animal tumor model." (PMID 23970998, 2013). "The use of tyrosine kinase inhibitors (TKIs) against EGFR/c-Met in non-small cell lung cancer (NSCLC) has been shown to be effective in increasing patient progression free survival (PFS), but their efficacy is limited due to the development of resistance and tumor recurrence." (PMID 24223799, 2013). "Thus, no adequate treatment options currently exist for EGFR-tumor-driven patients who have experienced EGFR-TKIs and chemotherapy failure." (PMID 27234384, 2013). "The effect of anti-EGFR therapy depends on whether the tumor has a KRAS mutation; anti-EGFR therapy is not effective for patients with a mutation in codon 12 or 13 of KRAS." (PMID 24040099, 2013). "Additionally, treatment response has not been correlated with alterations in EGFR expression and signaling activity within the tumor." (PMID 23963114, 2013). "Tumor tissue with high COX-2 74 kDa protein lacked EGFR protein." (PMID 24171795, 2013). "The rational selection of the first-line individualized therapy, between anti-EGFR therapy and anti-VEGF therapy, is only possible if the patient benefits of tumor KRAS mutation testing, whereas without this determination, the therapeutic choice would be done by default." (PMID 24133623, 2013). "Interestingly, our results showed that suppression of EGFR or Rictor alone did not significantly affect tumor growth in vivo, and had little impact on cell proliferation, apoptosis and migration in vitro." (PMID 23555046, 2013).